ASB3 (ankyrin repeat and SOCS box containing 3)
Description:
Probable substrate-recognition component of a SCF-like ECS (Elongin-Cullin-SOCS-box protein) E3 ubiquitin-protein ligase complex which mediates the ubiquitination and subsequent proteasomal degradation of target proteins. Recognizes TNFRSF1B. Plays a role in the down-regulation of antiviral innate immunity by targeting MAVS for ubiquitin-proteasomal degradation. Also destabilizes TRAF6 by enhancing its 'Lys-48'-linked polyubiquitination.
Synonyms: ASB-3; GPR75-ASB3
Tractability: PROTAC: ubiquitination databases record sites on it.
Gene: Protein-coding gene on chromosome 2 (53,532,672 to 53,860,160, reverse strand). Ensembl gene ENSG00000115239.
Subcellular location: Cytoplasm
Pathways (Reactome):
Immune System: Antigen processing: Ubiquitination & Proteasome degradation
Metabolism of proteins: Neddylation
Gene Ontology:
Molecular function: protein binding
Biological process: intracellular signal transduction; protein ubiquitination
Cellular component: cytoplasm; cytosol
Genetic constraint (gnomAD): Loss-of-function variants: 44 observed, 56.69 expected, observed/expected ratio (o/e) 0.78, 90% interval 0.61 to 1. The upper end of that interval is the gene's LOEUF score, 1, which puts it in group 4 of 6, group 1 being the genes least tolerant of losing a copy. Missense variants: 733 observed, 647.4 expected, observed/expected ratio (o/e) 1.13, 90% interval 1.07 to 1.2. Synonymous variants: 266 observed, 231.66 expected, observed/expected ratio (o/e) 1.15, 90% interval 1.04 to 1.27.
Homologues: Orthologues: chimpanzee ASB3 (99% identical), macaque ASB3 (98% identical), rabbit ASB3 (89% identical), dog ASB3 (89% identical), pig ASB3 (88% identical), rat Asb3 (84% identical), mouse Asb3 (84% identical), guinea pig ASB3 (76% identical), tropical clawed frog asb3 (58% identical), zebrafish asb3 (45% identical). Paralogues in human: ASB14 (29% identical), ASB15 (28% identical), ASB10 (19% identical), ASB18 (18% identical), ASB16 (18% identical), ASB4 (17% identical), MPHOSPH8 (14% identical).
Diseases named in the same sentence as ASB3 in open-access papers:
ASB3 is named in the same sentence as 17 diseases in open-access papers, as found by Europe PMC text mining. Sharing a sentence is not in itself a finding about the gene and the disease. The quoted sentences say what the papers report.
colorectal cancer (3 papers, 2017 to 2024). A primary or metastatic malignant neoplasm that affects the colon or rectum. "Although ASB3 genes have been extensively studied in oncological disorders, such as promoting colorectal cancer cell growth and metastasis when mutated or down-regulated, their connection with inflammation and IC remains unelucidated." (PMID 39399486, 2024). "This study aimed to investigate the effects of ASB3 on the growth and metastasis of colorectal cancer (CRC)." (PMID 28088228, 2017).
hepatocellular carcinoma (2 papers, 2022). A malignant tumor that arises from hepatocytes. "Zhang discovered that the circ-ASB3 inhibition could increase mitochondrial apoptosis and autophagy, which could accelerate cell death in hepatocellular carcinoma cells." (PMID 35492076, 2022).
asthma (1 paper, 2023). "The protein product of ASB3, via MAP kinase and Akt phosphorylation, regulates Erk1/2 and PI3K/Akt signal transduction pathways, being implicated in smooth muscle proliferation in asthma." (PMID 36835202, 2023). "Among the differentially co-expressed genes, eight were previously linked to asthma in genome- (MRPL14, ASB3, RHOBTB2) and epigenome-wide (CLC, EPS15, GPI, SSCRB4, STRN4) association studies and five were mentioned in the literature in the context of asthma (SLC19A1, MAEA, CLC, ATP1B1, and RECK)." (PMID 36835202, 2023). "Moreover, the differentially co-expressed genes, both up- and down-regulated in EA, were previously linked to asthma in the genome- (e.g., MRPL14, ASB3, RHOBTB2) and epigenome-wide (e.g., CLC, EPS15, GPI, SRCRB4D, STRN4) association studies." (PMID 36835202, 2023).
autism (1 paper, 2015). Persistent deficits in social interaction and communication and interaction as well as a markedly restricted repertoire of activity and interest as well as repetitive patterns of behavior. "Subject HI1739 possessed a non-synonymous missense mutation of the ASB3 gene located on chromosome 2 and related to the ankryin repeat gene family known to play a role in brain development and function including autism." (PMID 25574603, 2015).
colitis (1 paper, 2024). Inflammation of the colon. "ASB3 is associated with dysregulation of the colitis microbiota and promotes proinflammatory factors’ production by disrupting TRAF6 stability." (PMID 39162488, 2024). "Here, we investigated the physiological role of ASB3 in the intestine and found that ASB3-deficient mice exhibited reduced susceptibility to dextran sodium sulfate (DSS)-induced colitis." (PMID 39162488, 2024). "Our current studies showed that ASB3−/− mice had downregulated susceptibility to experimental colitis and preserved intestinal barrier function." (PMID 39162488, 2024). "In this study, we report a previously unidentified function of ASB3 deficiency in ameliorating DSS-induced colitis." (PMID 39162488, 2024). "We observed that ASB3-deficient mice acquired colitis resistance by protecting more Bacteroidota while reducing the sudden increase in Lactobacillus." (PMID 39162488, 2024). "ASB3−/− mice are resistant to dextran sodium sulfate-induced colitis." (PMID 39162488, 2024). "Strategies to limit the protein level of ASB3 in intestinal epithelial cells may help in the treatment of colitis." (PMID 39162488, 2024). "In summary, these data indicate that overactivation of ASB3 during the development of experimental colitis affects the composition of the intestinal microbiota and causes microbiota dysbiosis and that the latter may be due to the production of a large number of proinflammatory factors in these mice." (PMID 39162488, 2024).
glioma (1 paper, 2022). A benign or malignant brain and spinal cord tumor that arises from glial cells (astrocytes, oligodendrocytes, ependymal cells). "Our research tried to confirm the role of circ-ASB3 signal pathway in glioma progression and investigate its underlying mechanism." (PMID 35492076, 2022). "Finally our results revealed that circ-ASB3 could act as a new biomarker associated with the malignant progression of glioma and offer a potential therapeutic target for these patients." (PMID 35492076, 2022). "Circ-ASB3 was shown to increase glioma cell proliferation, invasion, and migration in vitro via miR-543/Twist1 axis." (PMID 35492076, 2022). "The signal pathway RNA and protein expression detection revealed that the circ-ASB3 and Twist1 gene expressions were significantly up-regulated while miR-543 gene expression was significantly down-regulated in high-grade glioma samples." (PMID 35492076, 2022). "Then, we conducted a series of in vitro assays and found that circ-ASB3 could promote glioma progression by regulating miR-543/Twist1 axis." (PMID 35492076, 2022). "The circ-ASB3/miR-543/Twist1 axis was discovered to be a possible regulatory pathway in glioma, circ-ASB3 could adsorb and targeted bind to miR-543, down-regulate miR-543 expression, thus release its targeted inhibition to Twist1." (PMID 35492076, 2022). "All these findings suggested that circ-ASB3 may enhance glioma malignant progression through miR-543/Twist1 axis." (PMID 35492076, 2022). "In this study, we hypothesized that GSCs containing circ-ASB3 could promote glioma progression by regulating the miRNA-mRNA network." (PMID 35492076, 2022). "The results of migration assay showed that in circ-ASB3 down-regulated glioma cells the transversely-migrated cells evidently decreased, while in glioma cells combined with miR-543 inhibition or Twist1 overexpression, the number of transversely-migrated cells correspondingly increased." (PMID 35492076, 2022). "According to the results of apoptosis detection, in circ-ASB3 down-regulated glioma cells the percentage of apoptotic cells increased significantly, while in glioma cells combined with miR-543 inhibition or Twist1 overexpression, the percentage of apoptotic cells correspondingly decreased." (PMID 35492076, 2022). "The results indicated that circ-ASB3 may be involved in the regulation of glioma pathological process." (PMID 35492076, 2022). "In summary, circ-ASB3 was significantly up-regulated in glioma stem cells, it could increase Twist1 expression by competitively inhibiting miR-543, thus promoting glioma malignant transformation." (PMID 35492076, 2022). "Therefore, our study investigated the functional roles of GSCs containing circ-ASB3 in glioma to provide new insights into the pathogenesis of glioma malignant progression." (PMID 35492076, 2022). "The results of invasion assay showed that in circ-ASB3 down-regulated glioma cells the vertically-migrated cells decreased significantly, while in glioma cells combined with miR-543 inhibition or Twist1 overexpression, the number of vertically-migrated cells correspondingly increased." (PMID 35492076, 2022). "Our findings revealed that GSCs contained circ-ASB3 could accelerated proliferation, invasion, migration and inhibit apoptosis of glioma cells through miR-543/Twist1 pathway." (PMID 35492076, 2022). "In our pre-experiment, we identified the differentially expressed circRNAs in GSCs and found that circ-ASB3 (Hsa_circ_0001005) was significantly up-regulated and may play a critical role in glioma progression." (PMID 35492076, 2022). "We aimed to examine the role of GSCs containing circ-ASB3 in glioma progression." (PMID 35492076, 2022). "In addition, circRNA pull-down assays were performed to validate the direct binding of circ-ASB3 and miR-543 in glioma cells." (PMID 35492076, 2022). "circ-ASB3 was significantly up-regulated in glioma stem cells compared with glioma cells." (PMID 35492076, 2022).
glioma (continued). "circ-ASB3 could enhance glioma malignancy via miR-543/Twist1 axis, resulting in the discovery of new biomarkers and possible therapeutic targets for these patients." (PMID 35492076, 2022). "The results of clone formation assay showed that in circ-ASB3 down-regulated glioma cells, the number of new cells obviously decreased, while in glioma cells combined with combined with miR-543 inhibition or Twist1 overexpression, the number of new cells correspondingly increased." (PMID 35492076, 2022). "By constructing GSCs specific circRNA-miRNA-mRNA regulatory network, exploring mRNA function, consulting relevant literatures and proceeding RT-PCR verification, we found that circ-ASB3/miR-543/Twist1 signal pathway may be closely related to the regulation of glioma biological characteristics." (PMID 35492076, 2022). "Moreover, through cell culture and RNA transfection we discovered that the down-regulation of circ-ASB3 could inhibit glioma proliferation, invasion and migration, meanwhile this down-regulation could also promote cell apoptosis and accelerate cell cycle." (PMID 35492076, 2022).
inflammatory bowel disease (1 paper, 2024). A spectrum of small and large bowel inflammatory diseases of unknown etiology. "Inflammatory bowel disease patients exhibit upregulated ASB3 expression at focal sites, supporting the involvement of degradation of TRAF6, which promotes TLR-Myd88/TRIF-independent NF-κB aberrant activation and intestinal microbiota imbalance." (PMID 39162488, 2024). "Sustained inflammatory signaling in intestinal epithelial cells and dysregulated protective probiotic immune responses mediated by ASB3 collectively contribute to the exacerbation of inflammatory bowel disease." (PMID 39162488, 2024).
interstitial cystitis (1 paper, 2024). A rare chronic debilitating urogenital disease characterized by urinary frequency, urgency, and pelvic pain. "Seven hub genes (SPTBN1, PSME4, CHAC2, ERLEC1, ASB3, STAT5A, and STAT3) were identified as differentially expressed between interstitial cystitis patients and healthy individuals, representing potential therapeutic targets." (PMID 39399486, 2024).
liver dysfunction (1 paper, 2026). "NR promotes liver regeneration after PVE in obese rats by enhancing NAD+-dependent metabolic pathways through the MCART1/ASB3 axis, offering a potential therapeutic strategy for obesity-associated liver dysfunction." (PMID 41493825, 2026).
renal cell carcinoma (1 paper, 2022). "We were surprised to find that renal cell carcinoma patients with high ASB3 expression were more responsive to anti-PD-1 targeted therapy." (PMID 36618381, 2022).
cancer (3 papers, 2022 to 2025). A tumor composed of atypical neoplastic, often pleomorphic cells that invade other tissues. "Previous studies have shown that ankyrin repeat and SOCS box-containing protein 3 (ASB3) is involved in immunomodulatory functions associated with cancer." (PMID 39162488, 2024). "ASB3 level was significantly negatively associated with Tregs and cancer-associated fibroblasts (CAFs)." (PMID 36618381, 2022). "The GSEA results suggested that ASB3 was closely linked to many important cancer and immune signaling pathways, mainly including cytokine, chemokine, antigen processing and presentation, focal adhesion and oxidative phosphorylation." (PMID 36618381, 2022). "In summary, our results indicated that ASB3 was aberrantly expressed in various cancers and significantly correlated with the prognosis of cancer patients." (PMID 36618381, 2022). "For different cancers, ASB3 expression will bring different prognosis outcomes, which is necessary to further study the specific role of ASB3 in each cancer." (PMID 36618381, 2022). "This study not only enriches the understanding of the biological function of ASB3 in pan-cancer, especially in GBM immunity, but also provides a new reference for the personalized immunotherapy of GBM." (PMID 36618381, 2022). "Our analysis showed that ASB3 expression was correlated with TMB in 8 cancer types and with MSI in 12 cancer types." (PMID 36618381, 2022). "According to the ranking of ASB3 gene activity in 33 cancer types, LGG and GBM were found to have the highest gene activity." (PMID 36618381, 2022). "In this study, we performed a comprehensive bioinformatics analysis using patient data from different databases to determine the functional role of ASB3 in a variety of cancers." (PMID 36618381, 2022). "In this study, we applied multiple bioinformatics methods to explore the expression level and gene activity of ASB3 in pan-cancer." (PMID 36618381, 2022). "Among the 25 cancer types containing normal tissues, the expression of ASB3 in 15 cancer types between normal tissues and tumors was statistically significant." (PMID 36618381, 2022). "Box plots showed the significant different activity distribution of ASB3 across normal and tumor samples in 13 cancer types." (PMID 36618381, 2022). "A comprehensive pan-cancer analysis of ASB3 showed its potential function as a biomarker of cancer prognosis and effective prediction of immunotherapy response." (PMID 36618381, 2022). "Box plots demonstrated the significant different expression distribution of ASB3 across tumor and normal samples in 15 cancer types." (PMID 36618381, 2022). "The results indicate that ASB3 may be a potential target for future cancer immunotherapy development." (PMID 36618381, 2022). "The results indicated that ASB3 have a regulatory effect on tumor immunity of several cancer types." (PMID 36618381, 2022). "The correlation between ASB3 and pan-cancer immune microenvironment was shown by heat map." (PMID 36618381, 2022). "At present, there are few systematic studies on ASB3 in pan-cancer, especially in GBM." (PMID 36618381, 2022). "Consequently, ASB3 may be a potential biomarker to predict the response to immunotherapy in patients with malignant tumors." (PMID 36618381, 2022). "We found that ASB3 was aberrant expressed in a variety of tumors, especially in GBM, and significantly correlated with the prognosis of cancer patients." (PMID 36618381, 2022). "Previous research has shown that ASB3 is a biomarker for HCC and CRC, but little is known about its role in other cancer types to date." (PMID 36618381, 2022). "To date, despite new evidence of the importance of ASB3 regulation in cancer development, its role in colonic inflammation has not been evaluated." (PMID 39162488, 2024). "ASB3 was dysregulated in many kinds of cancers, particularly in GBM, illustrating ASB3 might have certain functions in GBM and other cancers." (PMID 36618381, 2022).
cancer (continued). "The level of ASB3 was related to the TMB, MSI and immune cell infiltration in some cancer types." (PMID 36618381, 2022). "ASB3 had a negative association with immune infiltration and TME, including regulatory T cells (Tregs), cancer-associated fibroblasts, immunosuppressors and related signaling pathways in GBM." (PMID 36618381, 2022).
tumor (2 papers, 2017 to 2022). "WT ASB3 inhibits CRC cell proliferation, migration, and invasion in vitro and decreases the tumorigenicity and hepatic metastasis in vivo; whereas mutated ASB3 lost this tumor-suppressive role." (PMID 28088228, 2017). "This indicates that ASB3 inhibits CRC cell proliferation as a tumor suppressor and that dysfunctions of ASB3 resulting from mutations or down-regulation are among the possible events that lead to CRC pathogenesis or progression." (PMID 28088228, 2017). "The biological function of ASB3 in tumor-infiltrating lymphocytes (TILs) was verified using an animal model." (PMID 36618381, 2022). "We calculated the ASB3 gene activity of each sample by the ssGSEA algorithm and compared the ASB3 gene activity between normal and tumor groups." (PMID 36618381, 2022). "In intrasplenic injection models, we found that overexpressing WT ASB3 in HCT116 cells suppressed intrasplenic tumor formation and hepatic metastasis." (PMID 28088228, 2017). "Second, further studies are required to confirm what molecules ASB3 directly interact with to play the tumor-suppressive role in CRC tumorigenesis." (PMID 28088228, 2017). "We sorted the tumor types according to the gene expression levels of ASB3." (PMID 36618381, 2022). "Conclusively, ASB3 exerts a tumor-suppressive role in the pathogenesis and progression of CRC." (PMID 28088228, 2017). "Orthotopic tumor models were established using normal GL261 cells and ASB3 overexpression GL261 cells, respectively." (PMID 36618381, 2022). "Our current study demonstrated that not only ASB3 ΔSOCS mutant but also G135E, K339I, and G135E/K339I mutants that were detected in CRC cases lost the tumor-suppressive function of WT ASB3." (PMID 28088228, 2017). "IHC assay for 274 CRC samples showed that average ASB3 protein levels were significantly lower in tumor tissues than in paratumor mucosa (P < 0.001) and that 70.4% (193/274) of CRC cases exhibited a down-regulated expression in tumor tissues." (PMID 28088228, 2017). "qPCR and Western blotting assays showed that ASB3 mRNA levels were significantly lower in CRC tissues than in paired normal colorectal mucous epitheliums (n = 48, P = 0.016) and that ASB3 protein levels were lower in 75.0% (9/12) of tumor tissues than in paired normal epithelial tissues." (PMID 28088228, 2017). "Conversely, the ectopic overexpression of wild-type ASB3, but not that of ASB3 mutants that occurred in clinical CRC tissues, inhibited tumor growth and metastasis." (PMID 28088228, 2017).
intestinal diseases (1 paper, 2024). "The role of ASB3 in intestinal diseases is poorly studied and is currently only found to be upregulated in COAD." (PMID 39162488, 2024).
ASB3 also shares sentences with these, for which no sentence is quoted: glioblastoma multiforme (1 paper); infection (1); lupus nephritis (1); Obesity (1).